IRF3 (interferon regulatory factor 3)
Diseases named in the same sentence as IRF3 in open-access papers (continued):
Sharing a sentence is not in itself a finding about the gene and the disease.
Sepsis (continued). "However, the effects of FX-targeted IRF3 on the bacterial flora (which is disrupted in sepsis) and the mechanisms by which it impacts sepsis development remain unclear." (PMID 37762104, 2023). "However, the molecular mechanisms are unclear; whether RIKA-like activities play any role in the sepsis-promoting function of IRF3 needs to be investigated." (PMID 37515265, 2023). "In this study, we found that 67% H2 inhalation inhibited the activation of STING during sepsis, thereby reducing the phosphorylation of TBK1 and IRF3 and thus reducing the level of neuroinflammation." (PMID 40016173, 2025). "STING signaling promoted the p-IRF3 nuclear translocation, NLRP3 inflammasome priming, and transient DC pyroptosis, thereby exacerbating hyperinflammation in the acute phase of sepsis." (PMID 41647935, 2025). "Apigenin attenuates the LPS-induced inflammatory response by inhibiting the STING/IRF3 pathway, whereas UDCA mitigates sepsis-induced lung injury by blocking cell death via the STING pathway." (PMID 39737190, 2024). "These are achieved by disrupting the interactions between STING, TBK1, and IRF3, thereby reducing cGAS-STING pathway activation and mitigating sepsis-related damage." (PMID 39737190, 2024). "Fucoxanthin (FX), which is a carotenoid derived from brown algae, binds to IRF3 and inhibits the phosphorylation of IRF3, then reduces pro-inflammatory cytokine production, thereby decreasing mortality in a mouse CLP-induced sepsis model." (PMID 38375470, 2024). "From above, IRF3 functions as an immune protector through IFN production; however, IRF3 activation augments sepsis mortality." (PMID 38375470, 2024). "The composition of intestinal microbes in mice with CLP-induced sepsis was altered by treatment with FX, and the OTU quantity of the intestinal flora in mice with CLP sepsis was altered by IRF3." (PMID 37762104, 2023). "Additional studies showed phosphorylated IRF3 subsequently translocated into nucleus and increased the expression of NOD-like receptor protein 3 (NLRP3), leading to the development of sepsis and sepsis-induced cardiomyopathy." (PMID 36072862, 2022). "IRF3 signaling, one component of the TLR4 signaling pathway, has been highlighted to contribute to sepsis pathogenesis." (PMID 33869780, 2021). "Unlike the effects of IRF3 on sepsis, our study revealed that IRF7 was activated to clear bacteria and ultimately reduced the death rate of septic mice." (PMID 41212050, 2025). "Sepsis is a severe clinical syndrome due to the host response to infection, exacerbated by the production of both pro-inflammatory cytokines (TNF-alpha, IL-1-beta>alpha, IL-6, il-8, IL-12, IL-17, COX-2, IRF3) and anti-inflammatory (IL-10) cytokines." (PMID 39768405, 2024). "In addition, IRF3 (c.829G > A; p.Ala277Thr), a transcriptional regulator of type I interferon (IFN)-dependent immune responses, was overrepresented in the sepsis cohort (adjusted p = 0.012)." (PMID 34973142, 2022). "Flow cytometry analysis further revealed that downstream effectors of TLR9, including IRF3, MyD88, and TRAF3, were elevated in all of the sepsis patients compared with the normal donors, and was correlated with improved prognosis in patients with sepsis." (PMID 31534550, 2019).
HCMV infection (28 papers, 2014 to 2025). "HCMV infection causes about 30% of cells to exhibit IRF3 nuclear localization, while Eltanexor treatment alone leads to nearly 100% cells with nuclear localization of IRF3." (PMID 34012430, 2021). "Taken together, these findings demonstrate that latent HCMV infection activates the STING/p-TBK1/p-IRF3 signalling cascade but impairs p-IRF3 nuclear translocation." (PMID 40872823, 2025). "During HCMV infection of fibroblasts, some IRF3-dependent ISGs are upregulated to a similar extent by IRF3 or type I IFN-IFNAR signaling, and others are fully induced only when both pathways are activated." (PMID 37289084, 2023). "We observed that depletion of ATRX resulted in a suppressed innate immune response to HCMV infection, as detected by reduced phosphorylation of IRF3 and decreased IFNB1 transcription." (PMID 35939517, 2022). "Upon HCMV infection, cytoplasmic IRF-3 is phosphorylated and dimerized, and then translocated from the cytoplasm into the nucleus." (PMID 34012430, 2021). "While many cellular proteins utilize XPO1, of particular interest to HCMV infection is IRF3, which relies solely on XPO1 for its nuclear export." (PMID 34012430, 2021). "HCMV infection recruits a transcriptional complex containing interferon regulatory factor 3 (IRF-3) and acetyl transferases [CREB-binding protein (CBP) and p300] to the nucleus and thus stimulates type I IFN production." (PMID 34012430, 2021). "Literature suggests that several ISGs, including MX1 and ISG15, have been found to upregulated after human cytomegalovirus (HCMV) infection and behave in an interferon-independent, IRF3-dependent manner." (PMID 33419081, 2021). "These two observations combine to definitively demonstrate that the upregulation of ISG15 caused by HCMV infection can occur in an IFN-independent, IRF3-dependent manner." (PMID 30871003, 2019). "IFN-independent, IFN regulatory factor 3 (IRF3)-dependent interferon-stimulated gene (ISG) regulation in the context of CMV infection was first documented 20 years ago." (PMID 31921100, 2019). "Many of these IFN-independent, IRF3-dependent ISGs are among the most potently induced by CMV infection and examining the roles these genes play in the innate response to CMV is essential to understanding the ramifications of this non-canonical regulation." (PMID 31921100, 2019). "The phosphorylation levels of ERK1/2 (p-ERK1/2), NF-κB p65 subunit (p-p65), and IRF3 (p-IRF3) were increased in response to HCMV infection when compared to mock infection with the medium only." (PMID 29194430, 2017). "HCMV infection was reported to activate IRF3, a process that required STING, an endoplasmic reticulum-resident protein involved in DNA sensing." (PMID 24671169, 2014). "In this study, we investigated whether latent HCMV infection modulates the STING/p-TBK1/p-IRF3 pathway to influence CD34+ cell differentiation." (PMID 40872823, 2025). "However, a recent study reported that interferon regulatory factor 3 (IRF-3) expression upregulated ISGs in an IFN-independent manner in the context of HCMV infection." (PMID 34668726, 2021). "Induction of the IFN-independent ISG viperin during HCMV infection is known to be induced by either IRF3 or IRF1, binding directly to its promoter, and this may also be the mechanism of IFIT1, IFIT2, IFIT3, CXCL10, Mx1, Mx2 and ISG15 upregulation." (PMID 30871003, 2019). "Importantly, HCMV infection of THP-1 cells is known to trigger IRF3-mediated IFN responses in a cGAS/STING-dependent manner." (PMID 30755509, 2019). "HCMV infection rapidly induces the activation of IRF3 leading to the expression of IFNs and ISGs." (PMID 30241345, 2018). "Indeed, our findings in vitro and in vivo support that US9 facilitates MAVS degradation, disrupts the STING–TBK1 signaling axis, and impedes phosphorylated IRF3 into the nucleus during HCMV infection, resulting in inhibition of IFN-β expression." (PMID 29317664, 2018).
HCMV infection (continued). "Furthermore, the HCMV tegument protein pp65 has been indicated to inhibit IRF3 activation after HCMV infection." (PMID 25856589, 2015). "In addition, no detectable ISG15 protein expression was observed following HCMV infection in IRF3 knockdown CRISPR/Cas-9 clones indicating that IFN-independent control of ISG expression during HCMV infection of human fibroblasts is absolutely dependent on IRF3 expression." (PMID 30871003, 2019). "In the context of UL88-STOP-mCh HCMV infection, we also observed upregulation of the Type I interferons IFN-β and IFN-α2, although IFNα1, IFNα4, and IRF3 were similarly expressed after infection with TB40/E-mCh or UL88-STOP-mCh HCMV." (PMID 40638072, 2025). "Since the STING/p-TBK1 pathway normally activates p-IRF3, leading to its translocation into the nucleus and subsequent transcription of type I IFN genes, it is possible that latent HCMV infection modulates this process." (PMID 40872823, 2025). "In the context of human cytomegalovirus (HCMV) infection, ZBP1 amplifies HCMV-induced IRF3 activation and IFN-β expression." (PMID 38402193, 2024). "cGAS activity plays a major role in the STING/tank-binding kinase (TBK-1)/IRF3 pathway, activated by herpes simplex virus type 1 (HSV-1) and HCMV infection." (PMID 32351486, 2020). "Specifically, pp65 has been shown to modulate nuclear factor-κB (NF-κB) and interferon regulatory factors 3 (IRF3) activities, which cooperate to induce transcription of several cytokines such as IFN-β, which then counteracts HCMV infection." (PMID 32351486, 2020). "Several ISGs, including IFIT1, IFIT2, IFIT3, Mx1, Mx2, CXCL10 and ISG15 were found to be upregulated transcriptionally following HCMV infection independently of type I IFN-initiated JAK-STAT signaling, but dependent on intact IRF3 signaling." (PMID 30871003, 2019). "Quantification of ISG15 mRNA by qRT-PCR revealed significant IRF3-dependent, IFN signaling-independent upregulation during HCMV infection." (PMID 30871003, 2019). "When searching for a mechanism underpinning IFN-independent ISG induction during CMV infection, initial studies turned to the powerful transcriptional regulator involved in IFN production, IRF3." (PMID 31921100, 2019). "Consistent with in vitro data, HCMV infection shows that US9 is an important viral factor for promoting the reduction of mitochondrial MAVS expression and STING–TBK complexes, disrupting IRF3 nuclear translocation, and consequently inhibiting IFN-β production." (PMID 29317664, 2018). "While IFI16 induces cytokines, only cGAS activates STING/TBK-1/IRF3 and apoptotic responses upon HSV-1 and HCMV infections." (PMID 27935834, 2016). "To investigate the mechanism by which PML promotes ISG transcription, we compared levels of IRF3, STAT1, STAT2, and their activated forms in control and PML-knockdown HF cells after UV-HCMV infection." (PMID 25812002, 2015). "In the context of HCMV infection, ZBP1 enhances HCMV-induced IRF3 activation and IFN-β expression." (PMID 38402193, 2024). "Taken together, these data demonstrate that upregulation of this subset of ISGs by HCMV infection can occur independently of viral gene expression, in a manner that is dependent on IRF3 but not dependent on STAT1." (PMID 30871003, 2019). "During HCMV infection accumulation of both free and conjugated ISG15 can be partially inhibited by interfering with the canonical IFNAR signaling pathway with a JAK inhibitor but some IFN-independent, IRF3-dependent expression remains." (PMID 31921100, 2019). "Taken together these data demonstrate that whilst soluble IFNβ is a potent driver of STAT-1-dependent ISG15 upregulation during HCMV infection, there is a significant component of ISG15 expression mediated by a type-I IFN signaling-independent, IRF3-dependent mechanism." (PMID 30871003, 2019).
HCMV infection (continued). "This demonstrates firstly, that nPro/HFs are capable of upregulating ISG15 transcript and secondly that there is a soluble factor produced during HCMV infection that can induce ISG15 upregulation in a STAT1-dependent, IRF3-independent manner, most likely type I IFN." (PMID 30871003, 2019). "The cGAS-STING pathway may play an important role in the type I IFN pathway upon HCMV infection because KD of either cGAS or STING strongly abolishes activation of TBK1 and IRF3." (PMID 29018427, 2017). "Upon HCMV infection, the protein levels of the CDS interferon gamma inducible protein 16 (IFI16), as well as of the transcription factors IRF3 and NF-κB are steadily downregulated, indicating that viral proteins target these important determinants of CMV infection." (PMID 28542326, 2017). "HCMV infection of human foreskin fibroblasts induced NOD2, the downstream receptor-interacting serine/threonine-protein kinase 2 (RIPK2), resulting in phosphorylation of TANK-binding kinase 1 (TBK1) and interferon regulatory factor 3 (IRF3)." (PMID 26830977, 2016). "Because IRF3 can control ZAP expression and IRF-3 expression decreases over time in Merlin-infected cells, we also investigated if IRF3 expression could affect ZAP expression upon HCMV infection." (PMID 36916924, 2023). "This may explain why CHX fails to inhibit expression of these genes during HCMV infection and corroborates data demonstrating significant inhibition of transcription of each of these genes by IRF3-specific siRNA." (PMID 30871003, 2019). "Unfortunately, examining whether live HCMV can subsequently inhibit responses triggered by UV-HCMV is complicated by the fact that UV-HCMV represents an exceptionally potent stimulus of IRF3- and IFN-mediated antiviral innate responses, rendering cells highly refractory to normal HCMV infection." (PMID 30755509, 2019). "However, PML does not seem to control this HDAC activity during HCMV infection, since PML knockdown did not significantly affect IRF3 phosphorylation after UV-HCMV infection." (PMID 25812002, 2015). "An effect of HCMV infection on IRF3 has not previously been reported." (PMID 24906157, 2014). "In the context of the HCMV infection, Ashley and colleagues demonstrated that the promoters of several core IRGs, including IFIT1, IFIT3, MX1, and ISG15, are transcriptionally induced by the activation of the transcription factor IRF3 and therefore function independent of the IFN responses." (PMID 36552792, 2022).
Insulin resistance (26 papers, 2016 to 2026). Increased resistance towards insulin, that is, diminished effectiveness of insulin in reducing blood glucose levels. "Increased phosphorylation of hepatic IRF3 is observed in liver samples from fibrosis patients, and is associated with insulin resistance and abnormal blood glucose levels." (PMID 38233853, 2024). "In addition, IRF3 is an important transcriptional effector of the inflammatory response associated with insulin resistance and nutrient overload, and the expression of these genes was similarly observed in the present study." (PMID 37110462, 2023). "However, IRF3 is also associated with the alleviation of insulin resistance and the global knockdown of IRF3 has resulted in elevated levels of insulin resistance in mice." (PMID 35088922, 2022). "The role of IRF3 is complex, promoting adipose tissue inflammation and insulin resistance in some contexts, while preventing it in others." (PMID 39158380, 2025). "Conversely, other studies show that IRF3 prevents adipose tissue and hepatic inflammation, insulin resistance, and steatosis." (PMID 39158380, 2025). "Adipocyte-specific knockout of IRF3 protects male mice against high-fat diet-induced insulin resistance, whereas overexpression of IRF3 or AIG1 in adipocytes promotes insulin resistance on a high-fat diet." (PMID 38816388, 2024). "shRNA-mediated reduction of IRF3 fully abrogated poly I:C–induced insulin resistance in these cells." (PMID 38816388, 2024). "Taken together with the loss-of-function studies, these data strongly suggest that adipocyte IRF3 is both necessary and sufficient to promote insulin resistance in adipocytes, and that it does so in a cell-autonomous and species-independent manner." (PMID 38816388, 2024). "In contrast, in cultured 3T3-L1 adipocytes, IRF3 was needed for LPS (TLR4 ligand)- or polyinosinic-polycytidylic acid (poly (I: C)) (TLR3 ligand)-induced insulin resistance." (PMID 38164186, 2024). "The interaction of IRF3 with IKKβ inhibited proinflammatory IKKβ/NF-κB signalling in the liver, mitigating insulin resistance." (PMID 38164186, 2024). "In an early study, IRF3 exerted protective effects on mice with diet-induced hepatic insulin resistance." (PMID 38164186, 2024). "The role of IRF3 in insulin resistance varies by tissue, and further study with tissue-specific IRF3 knocked out is needed." (PMID 38164186, 2024). "Signaling through Tlr3 and Tlr4, which lie upstream of Irf3, induced insulin resistance in murine adipocytes, while Irf3 knockdown prevented insulin resistance." (PMID 39683552, 2024). "By inhibiting the proinflammatory IKKβ/NF-κB pathway, IRF3 mitigates insulin resistance in the liver." (PMID 39669992, 2024). "TLR3/4-IRF3 activation induced insulin resistance in murine adipocytes, while IRF3 knockdown prevented insulin resistance." (PMID 39384770, 2024). "The activation of IRF3 is believed to induce insulin resistance, whereas its inhibition prevents insulin resistance." (PMID 35088922, 2022). "It was also found that TLR13 can interact with interferon regulatory factor 3 (IRF3), resulting in a decrease in Akt phosphorylation, while knockdown of IRF3 prevents TLR13-induced insulin resistance and increases p-Akt." (PMID 36139760, 2022). "One study also observed that IRF3 in adipose tissue promotes adipose inflammation and insulin resistance." (PMID 36451736, 2022). "The interaction between TLR13 and IRF3 expression resulted in decreased AKT activity, whereas IRF3 knockdown prevented TLR13‐induced insulin resistance and increased p‐AKT." (PMID 35088922, 2022). "IRF3 has been implemented in the development of insulin resistance and suggested as a possible therapeutic target." (PMID 35088922, 2022). "The recruitment of IRF3 with TLR13 resulted in decreased AKT activity, whereas IRF3 knockdown prevented TLR13‐induced insulin resistance and increased p‐AKT." (PMID 35088922, 2022).